CX3CR1 (C-X3-C motif chemokine receptor 1)
Diseases named in the same sentence as CX3CR1 in open-access papers (continued):
Sharing a sentence is not in itself a finding about the gene and the disease.
heart failure (7 papers, 2017 to 2025). Inability of the heart to pump blood at an adequate rate to meet tissue metabolic requirements. "In a non-parasitic model, early β-adrenergic stimulation was shown to activate the cardiac CX3CL1/CX3CR1 axis, supporting transient concentric remodeling and delaying the progression to heart failure." (PMID 40936920, 2025). "This hypothesis is consistent with the findings found in past and present studies looking at FKN/CX3CR1 as a pathogenesis for heart failure, irrelevant of the aetiology of the heart failure itself." (PMID 37510939, 2023). "CTGF has been revealed to enhance the levels of inflammatory chemokines FKN, which is a newly identified membrane-bound chemokine and plays a vital role in the transition from compensated ventricular remodeling hypertrophy to heart failure through the G protein-coupled chemokine receptor CX3CR1." (PMID 29069788, 2017). "Therefore, identification of potential targets, such as CX3CR1, could provide ideal ground for anti-inflammatory immunotherapy, potentially avoiding progression of patients to future heart failure." (PMID 37510939, 2023). "Hence, suppression of CX3CR1 may be an important immunomodulatory therapeutic target to ameliorate pressure-overload induced heart failure." (PMID 33411754, 2021). "In this study, we were able to demonstrate that fractalkine receptor CX3CR1 expression is essential in the development of LV hypertrophy and heart failure in response to pressure overload." (PMID 33411754, 2021).
lung adenocarcinoma (7 papers, 2017 to 2025). A carcinoma that arises from the lung and is characterized by the presence of malignant glandular epithelial cells. "Furthermore, the downregulation of C-X3-C motif chemokine receptor 1 (CX3CR1) in lung adenocarcinomas is associated with an increased likelihood of metastatic spread to the brain." (PMID 39780275, 2025).
lupus nephritis (7 papers, 2015 to 2025). Glomerulonephritis in the context of systemic lupus erythematosus. "We speculate that a single loss-of-function nucleotide polymorphism of CX3CR1 in humans may result in an exacerbation of lupus nephritis." (PMID 38299151, 2023). "An altered gut microbiome may lead to lupus nephritis, and when combined with the loss of function of CX3CR1, it may increase the risk of renal failure." (PMID 38299151, 2023). "Increased FKN expression in the glomerulus and expression of CX3CR1 by glomerular CD16+ monocytes in murine proliferative lupus nephritis indicates that FKN induces homing of CX3CR1-positive mononuclear cells." (PMID 26348210, 2015). "The results of this study suggest that CX3CR1 is a key regulator of lupus nephritis." (PMID 40508161, 2025). "CX3CR1 antagonism delays the onset and ameliorates the progression of lupus nephritis in mice." (PMID 38299151, 2023). "Based on these findings, it is plausible that CX3CR1-positive Tph2 cells can preferentially migrate into lupus kidney via CX3CR1-CXCL1 axis and contribute to the lupus nephritis in combination with CD16+ monocytes." (PMID 38448723, 2024).
peritonitis (7 papers, 2010 to 2023). Inflammation of the peritoneum (tissue that lines the abdominal wall and covers most of the organs in the abdomen). "By contrast, during thioglycolate-induced peritonitis, numbers of mo-DCs increased only in WT mice, whereas mo-Macs increased in Cx3cr1-Etv6Δ mice." (PMID 36543959, 2023). "To investigate the relative contributions of CCR2 and CX3CR1 to monocyte/macrophage recruitment in vivo, we used a mouse model of thioglycollate-induced peritonitis." (PMID 21060874, 2010). "Using an unsupervised multiparametric analysis of blood Mo in steady state and after sterile peritonitis, we observed that CX3CR1 expression did not discriminate the CMo from the NCMo subsets." (PMID 32582197, 2020). "On the contrary, the absence of CX3CR1 gene had few effects on macrophage infiltration in other disease models such as thioglycolate-induced or cecal ligation and puncture-induced peritonitis." (PMID 30399192, 2018). "Thus, we performed the thioglycollate-induced peritonitis in heterozygous mice with a florescent gene report for chemokine receptors CX3CR1+/GFP (green) and CCR2+/RFP (red) in inbred mice strains CCR2+/RFP CX3CR1+/GFP." (PMID 28824619, 2017). "This contrasts with models of peritonitis and Listeria infection, in which the majority of the Ly6Clo, CX3CR1+ monocytes remain in the blood and do not enter inflamed tissues." (PMID 25469644, 2014). "Thus, in contrast to the CX3CL1/CX3CR1 axis, Lyve1 levels in macrophages negatively correlated with PGE2 levels in the course of peritonitis, indicating that Lyve1 might have a pro-resolving function." (PMID 37998039, 2023).
type 2 diabetes (7 papers, 2015 to 2025). "Two single-nucleotide polymorphisms (T280M and V249I), located in the coding sequence of human CX3CR1, which impact CX3CR1 expression and function, were associated with increased incidence of type 2 diabetes and metabolic syndrome, partially explained by altered monocyte-adipocyte interactions." (PMID 28993702, 2017). "Consistent with a proinflammatory state, several key cell surface antigens (Cd4, Cd68, Cd84), immune sensors (Cx3cr1, Clec7a), and macrophage genes (Axl, Slc11a1) were upregulated in hIAPP islets and in type 2 diabetes." (PMID 34554282, 2022). "As microglia are the principal cell for CX3CR1 mRNA expression in the brain, microglia were isolated from vehicle and AOM-treated mice cortices at coma using immunoaffinity isolation." (PMID 27561705, 2016).
atopic dermatitis (6 papers, 2009 to 2025). "In allergic asthma, CX3CR1 expression regulates Th2 and Th1 cell survival in the inflammatory lung, while, in atopic dermatitis, it regulate Th2 and Th1 cell retention into the inflammatory site." (PMID 32582168, 2020). "A general decrease in the frequency or expression of CX3CR1 on human monocytes has been shown in other conditions, for example, in patients with atopic dermatitis." (PMID 31700522, 2019). "Gene expression of the chemokine receptor CX3CR1 was also found to decrease; CX3CR1 and its ligand CX3CL1 have been reported to contribute to atopic dermatitis." (PMID 40077628, 2025). "CX3CR1 was also identified as a co-receptor together with CD4 for entry of HIV-1, and a role for CX3CR1-FKN-mediated inflammation has been suggested in various inflammatory diseases including vascular injury, atopic dermatitis and allergic airway diseases." (PMID 19223978, 2009).
autism (6 papers, 2014 to 2026). Persistent deficits in social interaction and communication and interaction as well as a markedly restricted repertoire of activity and interest as well as repetitive patterns of behavior. "Appropriate CX3CR1 activation is required for microglia-mediated synaptic pruning during early development and animal models deficient in this receptor display autism-like behaviours." (PMID 41504877, 2026). "For instance, it was demonstrated that mice lacking CX3CR1 had decreased functional brain connectivity, deficits in synaptic pruning, and behavioral changes associated with the autism phenotype, such as deficits in social interaction and increased repetitive behaviors." (PMID 26869989, 2016). "In contrast, the expression of microglial markers TREM2, DAP12, CX3CR1, and AIF1 were lower in autism tissue than in control tissue, with fold changes of 0.780 (P = 0.0056), 0.797 (P = 0.0083), 0.659 (P = 0.0029), and 0.808 (P = 0.0052), respectively." (PMID 24410870, 2014). "Nevertheless, given that there are some clinical reports indicating that the expression levels of microglia (TREM2, Cx3CR1) and astroglia markers (mainly GFAP) may contribute to autism pathology, suggest that astrocyte dysfunction may underlie the ASD phenotype observed here." (PMID 39024558, 2024).
chronic lymphocytic leukemia (6 papers, 2014 to 2025). "Interestingly, this CX3CL1/CX3CR1 axis has been identified as a deregulated pathway associated with various tumors, including multiple myeloma (MM) and chronic lymphocytic leukemia (CLL), playing a crucial role in the cross-talk between cancer cells and the TME." (PMID 38299154, 2023). "Beyond its effects on neuroinflammation, AZD8797 suppresses CX3CR1-positive monocyte-mediated tumor growth in chronic lymphocytic leukemia (CLL) cells (Zhong W, 2024)." (PMID 41424797, 2025). "In chronic lymphocytic leukemia, the fractalkine/CX3CR1 axis activates Akt and is involved in the interaction of chronic lymphocytic leukemia with the microenvironment." (PMID 28903329, 2017). "CX3CR1, a TNF target found to be down-regulated by SB225002 treatment, has been implicated in chronic lymphocytic leukemia attraction and adhesion to bone marrow stromal cells." (PMID 26302043, 2015). "Our group demonstrated the involvement of CX3CR1 in the crosstalk between neoplastic B cells and tumor microenvironment of patients with chronic lymphocytic leukemia (B-CLL)." (PMID 24799766, 2014).
cognitive decline (6 papers, 2019 to 2025). "Deletion of Ifngr selectively in long-lived CX3CR1+ CNS cells ameliorated the cognitive decline suggesting an interaction between long-lived CX3CR1+ CNS cells such as microglia, and CD8+ T cells in an IFN-II dependent manner." (PMID 40619428, 2025). "Inhibition of oxidative stress mediated by Aβ1-42 oligomers and the rescue of the fractalkine receptor CX3CR1 have been recently considered as novel therapeutic strategies to prevent neuronal loss and cognitive decline in AD pathology." (PMID 33926064, 2021).
endometriosis (6 papers, 2018 to 2023). The growth of functional endometrial tissue in anatomic sites outside the uterine body. "Thus, we speculate that endometriosis-induced persistent pain is associated with primary afferent neurons expressing FKN as well as FKN/CX3CR1/p38-MAPK pathway activation and enhanced microglial response in the dorsal horn." (PMID 30622457, 2018). "In contrast, P2X7 receptor promotes the maintenance of neuropathic pain through the FKN/CX3C/CX3CR1 pathway, which seems to be altered in endometriosis." (PMID 33198179, 2020). "Results from the current study indicated that the FKN/CX3CR1/p38-MAPK pathway was equally important in the pain model of sciatic endometriosis." (PMID 30622457, 2018). "Despite that FKN/CX3CR1 signaling produces different effects in different cells in the development of endometriosis-induced pain, the way of this signaling in pain process is consistent, that is, ligand receptor binding to form cell-cell crosstalk." (PMID 30622457, 2018). "Moreover, chemokine fractalkine CX3CL1 and its receptor CX3CR1 are upregulated in ectopic endometrium and they are involved in endometriotic pain conduction, based on the results of the endometriosis animal model." (PMID 33435569, 2021). "We concluded that the FKN/CX3CR1 signaling pathway might be one of the mechanisms of peripheral hyperalgesia in endometriosis, which requires further studies." (PMID 30622457, 2018). "Thus, blocking FKN/CX3CR1 signaling communication in the different aspects of pain process can alleviate or reverse the development of pain symptoms in endometriosis." (PMID 30622457, 2018). "The role for spinal FKN/CX3CR1 in the development of endometriosis-administration of FKN antibody not only reversed the behavioral hypersensitivity that developed in rats with sciatic endometriosis, but also decreased the expression of FKN/CX3CR1 in the spinal cord." (PMID 30622457, 2018). "Moreover, the CXC chemokine family and CXC chemokine receptors, along with chemokine fractalkine CX3CL1 and its receptor CX3CR1, have also been highlighted for their contribution in the development of the local inflammatory milieu and the formation of the peripheral hyperalgesia in endometriosis." (PMID 33435569, 2021). "In the ectopic endometrial lesions of a sciatic endometriosis model in rats, increased levels of FKN and s-FKN as well as CX3CR1 have been detected, with a positive correlation with the severity of hyperalgesia." (PMID 33198179, 2020). "To assess morphologic characteristics of endometriosis-like lesions—as well as expression and location of FKN/CX3CR1—we performed H&E staining, immunostaining, and western blotting analyses." (PMID 30622457, 2018). "CX3CR1+ non-classical monocytes showed an increase in CD91 in patients with mild endometriosis." (PMID 35421980, 2022).
inflammatory bowel disease (6 papers, 2012 to 2025). A spectrum of small and large bowel inflammatory diseases of unknown etiology. "A method of treating inflammatory disease (inflammatory bowel disease) in a subject diagnosed with one or more loss-or-function mutations in the CX3CR1 gene using a therapeutically effective amount of an anti-fungal agent (SQ109, voriconazole, fluconazole, etc.)." (PMID 36359313, 2022). "A novel circulating pro-inflammatory monocyte subset, defined by double positive, CCR2+CX3CR1+ cells, was recently described in patients with inflammatory bowel disease." (PMID 41254741, 2025). "Macrophages with a cell surface phenotype of CD11cHiCCR2+CX3CR1+ are found in the intestinal wall of subjects with inflammatory bowel disease and are thought to be derived from CD14+ monocytes." (PMID 32544188, 2020). "However, in active inflammatory bowel disease (IBD), the conversion process of pro-inflammatory monocyte-like cells cells (CD11chighCCR2+CX3CR1+) into tolerant tissues (CD11c–CCR2–CX3CR1–) is impeded." (PMID 39355844, 2024). "In inflammatory bowel disease (IBD), intestinal microvascular endothelial cells produce high amounts of fractalkine, and IBD mucosa as well as periphery contained significantly more CX3CR1+ cells than control." (PMID 22235377, 2012).
metabolic syndrome (6 papers, 2017 to 2025). A cluster of metabolic risk factors for CARDIOVASCULAR DISEASES and TYPE 2 DIABETES MELLITUS. "IR has been shown to increase plaque vulnerability by overexpressing the CX3CL1/CX3CR1 axis, which is one of the possible factors linking diabetes or metabolic syndrome with cardiovascular disease." (PMID 41153665, 2025). "CX3CR1 up-regulation in platelet-Mon1 monocyte aggregates in metabolic syndrome patients led to increased CX3CR1/CCR2-dependent platelet-Mon1 monocyte adhesion to dysfunctional arterial endothelium." (PMID 31109070, 2019). "Although both neutrophil- and eosinophil-platelet aggregates of metabolic syndrome patients showed increased CX3CR1 expression when compared with the control group (Heparin), neither expressed CX3CR1 after platelet dissociation (EDTA)." (PMID 31109070, 2019). "We found that the percentage of CX3CR1-expressing platelets was significantly higher in the metabolic syndrome group than in the controls and positively correlated with blood glucose levels." (PMID 31109070, 2019). "Interestingly, AZD8797 decreases inflammation and increases NO production, which suggests that CX3CR1 in metabolic syndrome is different from its normal state." (PMID 32532282, 2020). "Additionally, CX3CL1/CX3CR1 or CCL2/CCR2 axes are potential candidates for therapeutic intervention in cardiovascular disorders in metabolic syndrome patients, as their blockade impairs the augmented arterial platelet-Mon1 monocyte aggregate adhesiveness, which is a key event in atherogenesis." (PMID 31109070, 2019). "We characterized immune cell behavior in metabolic syndrome, its consequences, and the potential involvement of the CX3CL1/CX3CR1 and CCL2/CCR2 chemokine axes." (PMID 31109070, 2019). "A similar profile was detected in CD3+ lymphocytes from metabolic syndrome patients and the percentage of CD3+CX3CR1+ lymphocytes was found to positively correlate with blood glucose levels, with or without bound platelets." (PMID 31109070, 2019). "First, enhanced CX3CR1 expression was found in the platelets, platelet-neutrophil, -eosinophil, -Mon1 monocytes, and -CD8+ T cell aggregates, as well as in platelet-unbound Mon1 monocytes and CD8+ T lymphocytes of metabolic syndrome subjects." (PMID 31109070, 2019). "Additionally, in the total monocyte subpopulation, an increase in the percentage of CX3CR1-expressing cells was evident in the metabolic syndrome patients, irrespective of whether platelets were bound or unbound." (PMID 31109070, 2019). "Indeed, the augmented numbers of CX3CR1+ platelets are likely to be involved in the increased platelet-neutrophil, -eosinophil, -Mon1 monocytes, and -CD8+ T lymphocyte adhesion to the dysfunctional arterial endothelium in metabolic syndrome patients, but not in controls." (PMID 31109070, 2019).
osteosarcoma (6 papers, 2008 to 2025). A usually aggressive malignant bone-forming mesenchymal neoplasm, predominantly affecting adolescents and young adults. "CX3CL1 induced cell migration in human osteosarcoma cells via upregulating ICAM-1 expression mediated by CX3CR1/PI3K/Akt/NF-κBpathway44." (PMID 37770496, 2023). "Fractalkine induced cell migration by upregulating intercellular adhesion molecule-1 (ICAM-1) expression via CX3CR1/PI3K/Akt/NF-κB pathway in human osteosarcoma cells." (PMID 28903329, 2017). "The fractalkine/CX3CR1 axis activated ICAM-1 expression in osteosarcoma and promoted the migration of osteosarcoma cells." (PMID 28903329, 2017). "Our findings indicate that the fractalkine/CX3CR1 axis is correlated with tumor progression and promotes cell migration in osteosarcoma." (PMID 28903329, 2017). "For the first time, our study elucidated the role of the fractalkine/CX3CR1 axis in osteosarcoma, the most common bone tumor in children." (PMID 28903329, 2017). "CCR1, CCR2, CCR5, CCR7, CXCR4, CXCR5 and CX3CR1 were found to be expressed in 100% of the osteosarcoma samples tested." (PMID 18215331, 2008). "Next, to examine whether CX3CR1, the specific receptor of the ligand fractalkine, is involved in fractalkine-induced cell migration, comparison of CX3CR1 between hFOB1.19 and osteosarcoma is important." (PMID 28903329, 2017). "We examined the levels of CX3CR1 between hFOB 1.19 and osteosarcoma (MG63 and U2OS)." (PMID 28903329, 2017). "Inhibiting CX3CR1 can promote TAM polarization, thereby accelerating the progression of osteosarcoma." (PMID 41267985, 2025). "In our present study, we confirmed that the PI3K/Akt signal cascade is involved in fractalkine/CX3CR1-induced ICAM-1 expression and lung metastasis in osteosarcoma." (PMID 28903329, 2017). "Our results also demonstrated that CX3CR1/PI3K/Akt/NF-κB mediates ICAM-1 expression, subsequently regulating cell migration and lung metastasis in osteosarcoma." (PMID 28903329, 2017).